MICAL1 (microtubule associated monooxygenase, calponin and LIM domain containing 1)
Description:
Monooxygenase that promotes depolymerization of F-actin by mediating oxidation of specific methionine residues on actin to form methionine-sulfoxide, resulting in actin filament disassembly and preventing repolymerization. In the absence of actin, it also functions as a NADPH oxidase producing H(2)O(2). Acts as a cytoskeletal regulator that connects NEDD9 to intermediate filaments. Also acts as a negative regulator of apoptosis via its interaction with STK38 and STK38L; acts by antagonizing STK38 and STK38L activation by MST1/STK4. Involved in regulation of lamina-specific connectivity in the nervous system such as the development of lamina-restricted hippocampal connections. Through redox regulation of the actin cytoskeleton controls the intracellular distribution of secretory vesicles containing L1/neurofascin/NgCAM family proteins in neurons, thereby regulating their cell surface levels (By similarity). May act as Rab effector protein and play a role in vesicle trafficking. Promotes endosomal tubule extension by associating with RAB8 (RAB8A or RAB8B), RAB10 and GRAF (GRAF1/ARHGAP26 or GRAF2/ARHGAP10) on the endosomal membrane which may connect GRAFs to Rabs, thereby participating in neosynthesized Rab8-Rab10-Rab11-dependent protein export.
Synonyms: MICAL-1; MICAL; NICAL; FLJ11937; DKFZp434B1517; FLJ21739
Tractability: Small molecule: a structure with a bound ligand is known. Antibody: UniProt places it where antibodies can reach, with high confidence; its Gene Ontology location is reachable by antibodies, with high confidence. PROTAC: ubiquitination databases record sites on it; its protein half-life has been measured.
Gene: Protein-coding gene on chromosome 6 (109,444,062 to 109,465,968, reverse strand). Ensembl gene ENSG00000135596.
Subcellular location: Cytoplasm; Cytoplasm, cytoskeleton; Endosome membrane; Midbody
Subcellular location (Human Protein Atlas): Cytosol; Nucleoplasm; Primary cilium; Basal body; Plasma membrane
Pathways (Reactome):
Hemostasis: Factors involved in megakaryocyte development and platelet production
Gene Ontology:
Molecular function: actin binding; F-actin monooxygenase activity; FAD binding; NAD(P)H oxidase H2O2-forming activity; oxidoreductase activity, acting on paired donors, with incorporation or reduction of molecular oxygen, NAD(P)H as one donor, and incorporation of one atom of oxygen; protein binding; SH3 domain binding; monooxygenase activity; protein kinase binding; small GTPase binding
Biological process: actin filament depolymerization; cytoskeleton organization; signal transduction; sulfur oxidation; negative regulation of apoptotic process; regulation of regulated secretory pathway
Cellular component: cytoplasm; cytosol; endosome membrane; intercellular bridge; midbody; actin cytoskeleton; intermediate filament; plasma membrane; cytoskeleton; hippocampal mossy fiber expansion
Genetic constraint (gnomAD): Loss-of-function variants: 95 observed, 135.71 expected, observed/expected ratio (o/e) 0.7, 90% interval 0.59 to 0.83. The upper end of that interval is the gene's LOEUF score, 0.83, which puts it in group 3 of 6, group 1 being the genes least tolerant of losing a copy. Missense variants: 1,292 observed, 1,432.2 expected, observed/expected ratio (o/e) 0.9, 90% interval 0.86 to 0.94. Synonymous variants: 546 observed, 579.59 expected, observed/expected ratio (o/e) 0.94, 90% interval 0.88 to 1.01.
Homologues: Orthologues: chimpanzee MICAL1 (99% identical), macaque MICAL1 (97% identical), pig MICAL1 (87% identical), guinea pig MICAL1 (84% identical), rabbit MICAL1 (84% identical), mouse Mical1 (80% identical), rat Mical1 (78% identical), dog MICAL1 (76% identical), zebrafish mical1 (45% identical). Paralogues in human: MICAL3 (45% identical), MICAL2 (35% identical), MACF1 (15% identical), PLEC (14% identical), SPTBN2 (14% identical), SPTBN4 (13% identical), DST (13% identical), SPTBN1 (13% identical), SPTB (13% identical), SPTBN5 (13% identical), SYNE1 (12% identical), DMD (12% identical), and 24 more.
Diseases named in the same sentence as MICAL1 in open-access papers:
MICAL1 is named in the same sentence as 29 diseases in open-access papers, as found by Europe PMC text mining. Sharing a sentence is not in itself a finding about the gene and the disease. The quoted sentences say what the papers report.
breast carcinoma (12 papers, 2016 to 2025). "MICAL1 gene disruption in MDA MB 231 human breast cancer cells was also associated with F-actin rearrangements, impaired directional cell migration, and reduced xenograft tumor growth." (PMID 35627100, 2022). "MICAL1 overexpression has been associated with elevated ROS generation, which contributed to the increased invasiveness of a number of human breast cancer cell lines." (PMID 35627100, 2022). "Therefore, it is interesting to investigate the signalling mechanisms underlying the effect of MICAL1 on promoting breast cancer cell proliferation." (PMID 29524295, 2018). "MICAL1-induced breast cancer cell invasion relies on the ROS/PI3K/Akt signaling pathway, and inhibition of ROS activation can downregulate the MAPK/ERK pathway." (PMID 41305343, 2025). "Of note, MICAL1 exerts its effect on proliferation via reactive oxygen species (ROS)-sensitive PI3K/AKT/ERK signaling in breast cancer cells." (PMID 35501725, 2022). "Recent research shows that MICAL1 disruption attenuated breast cancer tumour growth and migration in vivo and MICAL1 related Rac1 activation facilitates hypoxia-induced gastric cancer cell migration." (PMID 36371204, 2022). "Activation of ROS-sensitive ERK/cyclin D pathway is an essential mechanism mediating breast cancer cell proliferation by MICAL1." (PMID 36575439, 2022). "Our previous work identified a novel link between MICAL1 and RAB upon EGF stimulation and found that MICAL1 was essential for maintaining invasive phenotype of breast cancer cells." (PMID 31019460, 2019). "The present study is a continuation of our previous study where we have proven that MICAL1 exerts a significant growth and invasion-promoting effects on breast cancer cells." (PMID 31019460, 2019). "MICAL1, a multidomain flavoenzyme, is strongly involved in the mechanisms that promote breast cancer cell proliferation and invasion." (PMID 31019460, 2019). "It has been found that EGF-induced breast cancer cell invasion is MICAL1-dependent, which forms complexes with RAB35." (PMID 31019460, 2019). "We noticed that depletion of MICAL1 markedly reduced cell proliferation in breast cancer cell line MCF‐7 and T47D." (PMID 29524295, 2018). "Together, our results suggest that MICAL1 exhibits its effect on proliferation via maintaining cyclin D expression through ROS‐sensitive PI3K/Akt/ERK signalling in breast cancer cells." (PMID 29524295, 2018). "Herein, we performed this study to assess the involvement of MICAL1 in breast cancer cell proliferation and to explore the potential molecular mechanism." (PMID 29524295, 2018). "All these results indicated a stimulatory function of MICAL1 in proliferation of breast cancer cells." (PMID 29524295, 2018). "While the role of MICAL1 is less clear, our findings in HNSCC cells and those of Deng and coworkers in breast cancer suggest that reduced MICAL1 supports mesenchymal to epithelial transition." (PMID 29876004, 2018). "In this study, we examined the effects of MICAL1 on breast cancer cell proliferation and found that MICAL1 exhibits its effects by regulating cyclin D expressions via ROS‐sensitive PI3K/Akt/ERK signalling." (PMID 29524295, 2018). "To further verify the impact of MICAL1 expression on breast cancer proliferation, we assessed cell cycle distribution." (PMID 29524295, 2018). "LY294002 treatment also attenuated the increase in the p‐ERK level in MICAL1‐overexpressed breast cancer cells." (PMID 29524295, 2018). "Taken together, these experiments demonstrated that both RAB35 and MICAL1 were required for ROS generation in breast cancer cells." (PMID 27430308, 2016). "Enhanced motility of breast cancer cells is a critical step in promoting tumor metastasis, but roles of MICAL1 in breast cancer motility remain to be determined." (PMID 27430308, 2016). "Until now, limited knowledge was concerning the regulation of MICAL1 function by EGF signaling in breast cancer cells." (PMID 27430308, 2016).
breast carcinoma (continued). "Our results showed that the migratory and invasive ability of breast cancer cells induced by EGF or FBS stimulation decreased significantly after MICAL1 silencing in vitro." (PMID 27430308, 2016). "Taken together, our results provide evidence that MICAL1 plays an essential role in the activation of ROS/Akt signaling and cell invasive phenotype and identify a novel link between RAB35 and MICAL1 in regulating breast cancer cell invasion." (PMID 27430308, 2016). "We also observed that MICAL1 silencing delayed the increased invasive ability of RAB35 (CA)-expressing breast cancer cells." (PMID 27430308, 2016). "Similar with those results, in the present study, we uncovered an essential role of MICAL1 in promoting migration and invasion of breast cancer cells." (PMID 27430308, 2016). "Our results provide evidence that MICAL1 plays an essential role in the activation of ROS/Akt signaling and cell invasive phenotype and identify a novel link between RAB35 and MICAL1 in regulating breast cancer cell invasion." (PMID 27430308, 2016). "In summary, these data suggest that MICAL1 may promote breast cancer cell proliferation by ROS‐PI3K/Akt signalling pathway activation." (PMID 29524295, 2018). "Overexpression of MICAL1 resulted in increased cyclin D in breast cancer cells." (PMID 29524295, 2018). "Our observations described MICAL1's effect on breast cancer cell proliferation and may help to better understand how deregulation of MICAL1 contributes to breast cancer progression." (PMID 29524295, 2018). "Taken together, we demonstrate for the first time that MICAL1 may play a potential role in breast cancer cell motility and shed light on new therapeutic target against breast cancer invasion and metastasis." (PMID 27430308, 2016). "We first explored the effects of MICAL1 silencing on breast cancer cell migration in vitro." (PMID 27430308, 2016). "Likewise, the over-expression of MICAL1 augmented the generation of ROS, increased Akt phosphorylation, and favored invasive phenotype of breast cancer cells." (PMID 27430308, 2016). "Herein, we tested whether MICAL1 could control cell migration and invasion through regulating ROS in breast cancer cell lines." (PMID 27430308, 2016). "Consistently, P-Akt was higher in MICAL1 overexpressed breast cancer cells." (PMID 27430308, 2016). "In conclusion, results obtained in this study clearly establish a new mechanistic connection between RAB35 and MICAL1 in the context of ROS generation, which could be essential in promoting cell migration and invasion during breast cancer cell metastasis." (PMID 27430308, 2016). "Although RAB35 could recruit different effectors to perform specific biological process, it remains unclear whether and if so, the biological relevance of RAB35 binding to MICAL1 in breast cancer cells." (PMID 27430308, 2016). "Moreover, we determine a novel link between RAB35 and MICAL1 in regulating EGF-induced breast cancer cell invasion." (PMID 27430308, 2016). "Here, we delineated the role of MICAL1 in regulating breast cancer cell motility." (PMID 27430308, 2016). "Therefore, Akt is more likely the target of ROS downstream of MICAL1 to regulate breast cancer cell motility." (PMID 27430308, 2016). "Recent study suggested that MICAL1 gene disruption could altered breast cancer cell cytoskeleton organization, cell morphology and inhibited cell migration, however, only a few reports have been published to describe the functions of MICAL1 during cancer progression." (PMID 36575439, 2022). "However, MICAL1 could also promote tumor progression in gastric cancer, melanoma, and breast cancer." (PMID 36371204, 2022). "In addition, inhibition of ERK activation by U0126 results in an decrease in cyclin D expression in MICAL1‐overexpressed cells, indicating that MICAL1‐induced breast cancer cell proliferation might be due to cyclin D expression by a p‐ERK dependent way." (PMID 29524295, 2018).
breast carcinoma (continued). "However, whether MICAL1 could influence cell metastatic property by regulating ROS level in breast cancer cells remains to be determined." (PMID 27430308, 2016). "In keeping with this idea, MICAL1-induced breast cancer cell invasion might be PI3K/Akt dependent." (PMID 27430308, 2016). "Consistently, overexpression of MICAL1 augmented the generation of ROS, activated PI3K/Akt signalling, and favored invasive phenotypes of breast cancer cells." (PMID 36575439, 2022). "To examine the function of MICAL1 in breast cancer progression, we silenced MICAL1 expression in human breast cancer MDA-MB-231 cells with siRNA for MICAL1." (PMID 27430308, 2016). "We screened the protein levels of MICAL1 and RAB35 in five breast cancer cell lines and found that those two proteins were abundantly expressed." (PMID 27430308, 2016). "Interestingly, depletion of MICAL1 significantly inhibited ROS production, decreased p‐ERK expression and unfavourable for proliferative phenotype of breast cancer cells." (PMID 29524295, 2018). "Collectively, these data indicated that MICAL1 may facilitate ROS generation, which leads to PI3K/Akt/ERK/cyclin D signalling activation and breast cancer cell proliferation." (PMID 29524295, 2018). "Therefore, it is proposed that during EGF stimulation, MICAL1, especially for its FAD domain, facilitates the production of ROS, helping to promote the migratory and invasive ability of breast cancer cells." (PMID 27430308, 2016). "Although the current study has contributed to the mechanistic understanding the role of MICAL1 in breast cancer cell migration and invasion, the issue as to how RAB35 precisely regulates MICAL1 in breast cancer cells is unlikely to be settled in this paper." (PMID 27430308, 2016). "Collectively, these data indicate that the activation of RAB35/MICAL1 may facilitate ROS generation, which leading to PI3K/Akt signaling activation and breast cancer cell invasion." (PMID 27430308, 2016). "Recently, results from our laboratory have shown that MICAL1 modulates reactive oxygen species (ROS) production, and the latter then activates phosphatidyl inositol 3‐kinase (PI3K)/protein kinase B (Akt) signalling pathway which regulates breast cancer cell invasion." (PMID 29524295, 2018). "In addition, p‐S6K, the mTOR pathway effector related to cell proliferation decreased after MICAL1 overexpression and increased after MICAL1 depletion, suggesting that the MICAL1 function in breast cancer cell proliferation was probably not mediated by mTOR/S6K signalling." (PMID 29524295, 2018).
melanoma (5 papers, 2015 to 2022). A malignant, usually aggressive tumor composed of atypical, neoplastic melanocytes. "While the most well-characterized functions of MICAL1 are associated with regulation of the organization of the central nervous system, it has been implicated in several different cancers, including breast, gastric, colorectal, and melanoma." (PMID 35627100, 2022). "In spite of its wide distribution in the nervous system, MICAL1 has been found expressed in various human normal cells as well as cancer cell lines, including melanoma and HeLa cells." (PMID 27430308, 2016). "Previous studies have shown that aberrant activation MICAL1 is a negative regulator of apoptosis and contributes to malignant progression of melanoma." (PMID 27430308, 2016). "We also found high expression of both Sema6A and Mical1 in BRAFV600E cells derived from seven different melanoma cell lines isolated from primary tumor or from lymph node metastases." (PMID 25576923, 2015). "In conclusion our results revealed that BRAFV600E melanomas express high level of Sema6A and MICAL1 whose functions are strongly involved in the mechanisms that control cell proliferation and survival." (PMID 25576923, 2015). "Real-time PCR, Western blot and immunohistochemistry confirmed preferential expression of Sema6A and Mical1 in BRAFV600E melanoma." (PMID 25576923, 2015). "Furthermore, the depletion of MICAL1 in BRAFV600E-expressing melanoma cells led to an increase in cell apoptosis." (PMID 35627100, 2022). "We tested whether Sema6A and Mical1 could exert a significant pro-tumoral role in BRAFV600E melanomas by contributing to regulate their growth, survival, and invasion." (PMID 25576923, 2015). "Indeed, silencing of Mical1 in BRAFV600E melanoma clones (2/59, 2/56) and in 10538 melanoma cell line caused strong NDR phosphorylation between 30 h and 36 h post transfection associated with PARP cleavage." (PMID 25576923, 2015). "Overall, our data suggest that Sema6A and Mical1 may represent new potential therapeutic targets in BRAFV600E melanoma." (PMID 25576923, 2015). "Taken together, these results support the notion that both Sema6A and Mical1 promote cell survival, and inhibit cell death of BRAFV600E melanomas through different pathways." (PMID 25576923, 2015). "In attempts to find molecules regulating aggressiveness of BRAFV600E melanoma cells, by whole-genome array we found that SEMA6A and MICAL1, two genes of the SEMA/PLEXIN signaling pathway, were over-expressed in BRAFV600E clones compared to NRASQ61R clones isolated from the same metastasis." (PMID 25576923, 2015). "Surprisingly, Mical1 silencing did not change the actin cytoskeleton organization, indicating that its role in BRAFV600E melanoma cells is not overlapping with that of Sema6A." (PMID 25576923, 2015).